CASP1 (caspase 1)
Diseases named in the same sentence as CASP1 in open-access papers (continued):
Sharing a sentence is not in itself a finding about the gene and the disease.
Obesity (continued). "In individuals with obesity, an excursion into hyperglycemia following ingestion of a glucose load augments LPS-induced activation of caspase-1 in monocytes with no apparent impact of raising circulating β-OHB concentration via ingestion of exogenous ketones." (PMID 32209983, 2020). "We found that CASP11 was primarily present in CD11b+ cells; however, the cleaved CASP11 was lower in tumours from HFD mice, suggesting that CASP1 but not CASP11 is activated in tumour-infiltrating myeloid cells under obesity." (PMID 27708283, 2016). "Using mouse diet-induced obesity models, targeting various components of the inflammasome, including NLRP3, caspase-1 and ASC was shown to either prevent obesity, and/or to relieve obesity-induced manifestations, in particular whole-body insulin resistance and hepatic steatosis." (PMID 23341960, 2013). "In summary, the absence of caspase-1 ameliorates the injurious effects of high fat diet-induced obesity on the liver." (PMID 23409132, 2013). "We cannot rule out the possibility that caspase-1 is active in these tissues earlier or later in the WD-induced obesity model and that we may have missed these measurements at the time of our study endpoint." (PMID 35466363, 2022). "Thus, cAMP/PKA-signaling regulated by PDE3B in adipose tissue and potential targeting of caspase-1 activation through NLRP3 inflammasome, may be a new therapeutic target for the development of anti-obesity and anti-inflammatory drugs." (PMID 27321128, 2016). "Absence of caspase-1 protects from high fat-induced obesity." (PMID 23409132, 2013). "On the other hand, caspase-1 activity in NLRP3-deficient obese mice decreases but is not abolished in the presence of inflammasome inducers, suggesting that inflammasome “priming” plays a role at least in the pathophysiology of obesity." (PMID 22768222, 2012). "Moreover, aerobic exercise could ameliorate obesity-induced inflammation and vascular dysfunction by suppressing NLR family pyrin domain containing 3 (NLRP3) inflammasome, concomitantly reducing the levels of caspase-1 and IL-1β." (PMID 37859981, 2023). "Moreover, the biochemical analysis showed that obesity increased the caspase-1 activity and IL-1β production in Asm+/+ mice but not in Asm−/− mice, suggesting the essential role of Asm gene in mediating the obesity-induced NLRP3 inflammasome formation and activation in glomeruli of mice." (PMID 26980705, 2016). "In HFD, caspase-1 cleaves an inactivated SIRT1 protein in adipose tissues, and the adipocytes in the absence of the SIRT1 gene show spontaneous obesity." (PMID 32545788, 2020).
Cognitive impairment (76 papers, 2018 to 2026). Abnormal cognition is characterized by deficits in thinking, reasoning, or remembering. "Hitherto, the NLPR3/caspase-1 mediated pyroptosis pathway has been implicated in cognitive impairment in cerebral ischemia/reperfusion injury, Alzheimer's disease and perioperative neurocognitive disorders." (PMID 39698584, 2024). "In mice, Casp1 genetic ablation or VX-765 small molecule inhibition of Casp1 given at onset of cognitive deficits strongly supports the association between microglial inflammation and cognitive impairment." (PMID 36220815, 2022). "Deficiency of NLRP3 and caspase-1 resulted in protection from cognitive impairment and memory loss in an APP/PS1 mouse model of Alzheimer's disease." (PMID 33534121, 2021). "Preventing cognitive decline with VX-765 suggests that mutant APP expression in J20 mice causes cognitive impairment via Casp1-mediated inflammation." (PMID 32917871, 2020). "It is likely that VX-765 may prevent an early APP mutant-mediated and Casp1-dependent deleterious neuronal pathway that causes cognitive deficits and also controls subsequent microglial activation." (PMID 32917871, 2020). "An NLRP3-caspase-1 pathway inhibitor could attenuate the cognitive impairment caused by isoflurane anesthesia in the aged mice." (PMID 29665808, 2018). "In a homocysteine-induced cognitive impairment model, an independent risk factor for AD, betaine alleviated cognitive impairment by inhibiting the NLRP3/caspase-1/GSDMD pathway in an m6A-YTHDF2-dependent manner, thereby suppressing microglial pyroptosis." (PMID 41608511, 2026). "Retinal NLRP3 is elevated in mild cognitive impairment and activated in AD dementia, evidenced by increased caspase-1, cleaved interleukin-1β, and cleaved N-terminal gasdermin-D." (PMID 41571675, 2026). "NLRP3 was one of the most studied member in this family, and genetic deletion of NLRP3 or its downstream factor caspase-1 in AD mouse model resulted in reduced Aβ deposition, alleviated cognitive impairment, and decreased neuroinflammation." (PMID 40066444, 2025). "Inhibition of caspase-1 has been shown to effectively ameliorate cognitive impairment in AD mice, suggesting that caspase-1 inhibitors have potentials to be used for neurodegenerative diseases." (PMID 39710713, 2024). "Isoflurane induces hippocampal inflammatory responses and cognitive deficits through activation of the NLRP3/caspase-1 axis." (PMID 37962460, 2024). "Specifically, MINO effectively rectified the LPS-induced cognitive impairment by effectively suppressing the NLRP3/caspase-1 signaling." (PMID 38329438, 2024). "The NLRP3/Caspase-1 pathway-induced pyrodeath can result in cognitive impairment in SAE mouse models." (PMID 39027435, 2024). "Elucidating this will ascertain the role of caspase-1 in myelin regeneration, which has remained unstudied and necessary since white matter dysfunction precedes the onset of cognitive impairment." (PMID 38630707, 2024). "Intense active expression of caspase-1 has been detected in the brains of individuals with mild cognitive impairment and dementia due to AD." (PMID 38419122, 2024). "In summary, the results show that the activation of the NLRP3/Caspase-1/IL-1β signaling pathway negatively regulates the hippocampal neuroinflammation and cognitive impairment induced by LPS." (PMID 36934348, 2023). "In APP/PS1 mice, the simultaneous silencing of NLRP1 and caspase-1 reduced neuronal cell death in the cortex and hippocampus, and improved cognitive impairment." (PMID 37921870, 2023). "It has been determined that the NLRP3/caspase-1 pathway plays a crucial role in isoflurane-induced cognitive impairment." (PMID 37179548, 2023). "In this study, we explored the potential role of the Hsp22/NLRP3/Caspase-1/IL-1β axis in LPS-induced hippocampal neuroinflammation and cognitive impairment in mice." (PMID 36934348, 2023). "It has also been proved that inhibitors of Caspase-1 can alleviate cognitive impairment of AD model mouse." (PMID 35172755, 2022).
Cognitive impairment (continued). "Studies showed NLRP1 expression was up-regulated in the brain tissue of APP/PS1 mice, however, using NLRP1 inhibitor decreased caspase-1 and IL-1β expression, reduced neuron pyroptosis, and finally improved cognitive impairment." (PMID 35782390, 2022). "Reversal of cognitive deficits with VX-765 is likely due to reversal of neuronal degeneration, which is induced via the Nlrp1 inflammasome-Casp1-Casp6 neurodegenerative pathway." (PMID 36220815, 2022). "The levels of cleaved caspase-1 were increased in the brain of patients with Alzheimer’s disease and mild cognitive impairment." (PMID 33534121, 2021). "In vivo experiment, isoflurane induced microglial inflammation and cognitive impairment in aged mice through the NLRP3-Caspase-1 pathway." (PMID 34497527, 2021). "Inflammatory Caspase-1 has a significant impact on AD-like pathophysiology and Caspase-1 inhibitor, VX-765, reverses cognitive deficits in AD mouse models." (PMID 32917871, 2020). "In patients with early AD or mild cognitive impairment due to AD, levels of IL-1β and caspase-1 activity are significantly increased and ASC-bound Aβ is found in AD patients' brains." (PMID 32391019, 2020). "Together, these results indicate that preventing Casp1-mediated inflammation pre-symptomatically with a VX-765 short-term treatment is sufficient to delay the onset of cognitive deficits in J20 mice." (PMID 32917871, 2020). "Our results suggest that the NLRP3/caspase-1 pathway-induced pyroptosis mediates cognitive deficits in a mouse model of SAE." (PMID 30276509, 2019). "This study is carried out to determine the critical role of the NOD-like receptor protein 3 (NLRP3)-caspase-1 pathway in isoflurane-induced cognitive impairment." (PMID 29665808, 2018). "This is a response to readers' comments on our paper entitled "Critical role of NLRP3-caspase-1 pathway in age-dependent isoflurane-induced microglial inflammatory response and cognitive impairment" published in the Journal of Neuroinflammation this year." (PMID 30217141, 2018). "The NLRP3 inflammasome complex is considered a possible therapeutic target for preventing various cognitive impairments due to its response to microbial infections and environmental stimuli, and it can activate caspase-1 and promote the maturation of IL-1β and IL-18." (PMID 39203778, 2024). "Caspase-1 activation and proinflammatory cytokine release preceded the alteration of AD pathology and cognitive impairment, which might suggest that NLRP3 activation occurred in the early stage of AD." (PMID 39109268, 2024). "These cognitive deficits were associated with significant increases in the levels of NLRP3, ASC, caspase-1, phosphorylated IκB-α, and p65 levels in the hippocampus, emphasizing the pivotal role of the NLRP3 inflammasome in both surgery and anesthesia-induced POCD." (PMID 39411285, 2024). "We speculate that probiotics therapy might effectively reconstruct the balance of the intestinal microbiome, which could somewhat inhibit the NLRP3/caspase-1 pathway, thus suppressing inflammatory responses and ameliorating cognitive impairment." (PMID 37179548, 2023). "Similar to previous research results, our results show that Hsp22 overexpression pretreatment can inhibit the expression of NLRP3, Caspase-1, IL-1β and proinflammatory cytokines in hippocampal neurons, improve cognitive impairment in mice, and improve learning and memory capabilities." (PMID 36934348, 2023). "Many studies have demonstrated that CASP1 may be a therapeutic target against cognitive impairment and inflammation in AD." (PMID 36466169, 2022). "Studies have proven that the cognitive impairment caused by isoflurane is related to the high expression of hippocampus NLRP3, and this damage could be reversed by inhibiting the NLRP3-caspase-1 pathway." (PMID 35153623, 2022).
Cognitive impairment (continued). "In addition, caspase-1 activation is associated with brain pathology of AD and caspase-1 inhibition alleviates cognitive impairment and neuropathology in AD mouse models." (PMID 34975454, 2021). "Previous work showed that the caspase 1 inhibitor VX-765 rescued cognitive deficits in the J20 mouse model of Alzheimer’s disease, and this may occur via reduced inflammation." (PMID 32917871, 2020). "Moreover, an intensely active IL-1β-producing caspase-1 was detected in human mild cognitive impairment (MCI) brains and in frankly symptomatic AD brains." (PMID 33261147, 2020). "Thus, we further investigated the role of NLRP3/caspase-1-mediated pyroptosis in cognitive deficit of SAE mice." (PMID 30276509, 2019). "Consequently, Nlrp1, Casp1, and Casp6 represent feasible therapeutic targets against age-dependent cognitive deficits and AD." (PMID 30254377, 2018). "The relative expression levels of NLRP3 (p < 0.05), ASC (p < 0.05), and Caspase-1 (p< 0.05) in the jejunum of the model group were significantly increased, indicating that intestinal inflammation was increased in mice with cognitive impairment induced by sleep deprivation." (PMID 40232008, 2025). "In addition, decreases in the expression levels of ASC, Caspase-1, and IL-1β/IL-18 have been shown to alleviate the cognitive impairment of gerbils after I/R, and ASC exacerbates ischemic neurological deficits and inflammatory reactions in an NLRP3-dependent manner." (PMID 38441564, 2024). "Therefore, targeting the NLRP3-Caspase-1-IL-1β signaling axis may be an important way to improve cognitive impairment, although the exact activation mechanism is unknown." (PMID 36934348, 2023). "Therefore, AS-IV may improve cognitive impairment by binding to AD-related gene, such as caspase-1, TRPV1, PSEN1, and GSK3Β, reduce cell death, and ultimately inhibit AD-phenotypes." (PMID 34616501, 2021). "NLRP3 or caspase-1 deficiency in APP/PS1 mice leads to reduced brain caspase-1 and IL-1β activation, increased microglial Aβ phagocytosis, reduced brain Aβ load, and protection of neuronal spine loss, long-term potentiation (LTP) decline, and cognitive deficits." (PMID 32391019, 2020). "We found that isoflurane GA caused upregulations of hippocampal NLRP3, cleaved caspase-1, interleukin-1β (IL-1β), and IL-18 and the activation of pyroptosis, which is NLRP3 inflammasome-dependent; this consequently gave rise to neuronal damage and cognitive impairment in aged mice." (PMID 30524241, 2018). "Conversely, downregulation of microglial NLRP3 inhibited caspase-1 activation and pyroptosis, reduced release of IL-1β, improved AHN, and rescued cognitive deficits in DE mouse model." (PMID 41862685, 2026). "Inhibiting NLRP3 using MCC950 or caspase-1 using Ac-YV AD-CMK can reduce mortality, reverse cognitive impairment, and salvage neuronal damage." (PMID 39027435, 2024). "Blocking the NLRP3 inflammasome pathway with the caspase-1 specific inhibitor AC-YVAD-CMK prevents motor and cognitive impairments in HIBD models." (PMID 37620837, 2023). "In contrast, caspase-1 inhibitor VX765 treatment in Tregs-depleted mice successfully reversed increased microglial pyroptosis and restored myelin injury as well as cognitive defects aggravated by Tregs depletion." (PMID 36803990, 2023). "It is necessary to clarify the potential mechanism of Hsp22 in neuroinflammation-mediated cognitive impairment and the role of Hsp22 in regulating the activation of the NLRP3/Caspase-1/IL-1β pathway." (PMID 36934348, 2023). "It has been proposed that the Caspase-1 inhibitor VX765 suppressed the expression of GSDMD and its cleavage form GSDMD-N, which diminished microglia activation and protein cognitive impairment." (PMID 35401226, 2022). "In contrast, an identical VX-765 treatment regimen and Casp1 KO in 5- to 8-month-old J20 normalized Iba1+-microglia, elevated hippocampal TNF-α and CXCL1, and reversed or prevented the onset of cognitive impairment." (PMID 36220815, 2022).
Cognitive impairment (continued). "An in vivo knockdown of NLRP1 or (pro)caspase-1 in B6C3-Tg mouse brains significantly decreased neurons’ pyroptosis and mitigated cognitive impairment." (PMID 33261147, 2020). "In this study, we show that administration of either the NLRP3-inhibitor MCC950 or the caspase-1 inhibitor Ac-YVAD-CMK reduces mortality, reverses cognitive impairments, and rescues neuronal damages in mice that have undergone CLP." (PMID 30276509, 2019). "In addition, a single clinically relevant dose of ketamine (7 mg/kg) can induce an inflammatory reaction and cognitive impairment in the hippocampus of developing rats, which is related to activation of the NLRP3 inflammatory body/caspase-1 axis." (PMID 37962460, 2024). "Additionally, surgery led to increased expression of P2X7 receptors and its downstream protein caspase-1, and P2X7 receptor inhibition alleviated neuroinflammation and cognitive impairment." (PMID 37450925, 2023). "With this regard, expressions of NLRP3, GSDMD-NT, and cleaved caspase-1 were augmented in the brain of septic mice, and the upregulation of NLRP3, caspase-1, and gasdermin-D in the hippocampus resulted in the cognitive deficits in the mice model of SAE by inducing pyroptosis." (PMID 35832175, 2022). "In this study, caspase-1 inhibition by VX-765 significantly improved cognitive impairment and secondary degeneration in the nonischemic hippocampus after focal cortical infarction." (PMID 36441377, 2022). "We found that Caspase-1 variant was significantly associated with FDG PET levels and CSF t-tau levels at baseline in total non-demented elderly group, and especially in mild cognitive impairment (MCI) subgroup." (PMID 35172755, 2022). "Therefore, inflammasome NLRP3, ASC, caspase-1, GSDM-D, IL-1β, and IL-18 are key signaling molecules for inflammation and cell pyroptosis and are involved in the process of CI and other cognitive disorders." (PMID 31781266, 2019). "To ascertain whether treatment with A. muciniphila prevented cognitive impairment by inhibiting hippocampal NLRP3‐mediated neuroinflammation activation, we assessed the expression levels of ASC, Cleaved Caspase 1, IL‐18, NF‐κB, p‐NF‐κB and NLRP3 in the hippocampus after the behavioral study." (PMID 40050112, 2025). "Additionally, the role of the AIM2 inflammasome was examined in stroke-induced cognitive impairment in elderly mice, which demonstrated that AIM2 mRNA and protein, combined with caspase-1, IL-1β, and IL-18, were enhanced in the hippocampus and cortex after stroke." (PMID 37450925, 2023). "Therefore, our findings suggest that the NLRP3 inflammasome may be a new therapeutic target for cognitive impairment, and that targeting the NLRP3/Caspase-1/IL-1β signaling axis is a promising approach for the treatment of postoperative inflammation." (PMID 36934348, 2023). "Injection of Ac-YVAD-cmk (an NLRP3/caspase 1 inhibitor) prior to anesthesia did improve cognitive impairments and prevent hippocampal inflammation in aged mice, but not in young mice, which was possibly due to the attenuation of isoflurane-triggered NLRP3 inflammasome." (PMID 36503642, 2022). "In AD transgenic mice, Aβ treatment induced a high level of caspase-1 and IL-1β in the brain tissue, whereas the inhibition of either NLRP3 or caspase-1 in an AD mouse model increased the clearance of Aβ by microglia, reduced the Aβ deposition, and improved cognitive impairment." (PMID 32998318, 2020). "Thus, we hypothesized that the NLRP3/caspase-1 pathway is involved in NLRP3-mediated pyroptosis, maturation and release of inflammatory cytokines, and cognitive deficits in SAE." (PMID 30276509, 2019). "In individuals with mild cognitive impairment (MCI), NLRP3 expression was elevated, but PYCARD or caspase 1 was not, indicating that functional inflammasomes were not assembled." (PMID 40538660, 2025).
Cognitive impairment (continued). "Chinese herbal compound Naofucong has been mainly used to treat cognitive disorders in Traditional Chinese Medicine The present study aimed to investigate whether its neuroprotective effects might be related to the inhibition of P2X7R/NLRP1/caspase-1 mediated neuronal injury or not." (PMID 34093185, 2021).